PITX1 (paired like homeodomain 1)
Diseases named in the same sentence as PITX1 in open-access papers (continued):
Sharing a sentence is not in itself a finding about the gene and the disease.
cancer (continued). "Notably, immune analysis demonstrates a positive correlation between PITX1 and TIC in the context of CHS, as well as pan-cancer analysis." (PMID 40342824, 2025). "Endocrine system development and cancer growth-related ceRNA regulation are found in TNBC; HOXA5, SCAPER, PAK6, PBX1, PITX1, and ALOX15B are the relevant genes involved; and hsa-miR-296-5p, hsa-miR-185-5p, hsa-miR-7851-3p, hsa-miR-3187-3p, and hsa-miR-10396b-5p are the relevant miRNAs involved." (PMID 37483500, 2023). "Hence, PITX1 was rather described as a suppressor of TERT expression and telomerase activity in cells of this other cancer type." (PMID 35267575, 2022). "A band at 49 kDa corresponding to FLAG-tagged PITX1 was detected in these cancer cells, but not in control cells, on Coomassie brilliant blue (CBB) and silver stained gels." (PMID 31404068, 2019). "It is possible that there are other negative regulatory factors and component proteins in the PITX1-ZCCHC10 complex on human chromosome 5 for functional hTERT control, which would ultimately lead to a large discrepancy in suppression of hTERT transcription in cancer cells." (PMID 31404068, 2019). "PITX1, CST6 and HOPX were reported their downregulation in various types of human cancer, and PRSS27 was known to be highly expressed in nonkeratinizing stratified squamous epithelia of human esophagus and its dysregulation was supposed to be related to characteristics of carcinoma." (PMID 29137437, 2017). "However, studies on PITX1 as a prognostic marker for cancer grade are still relatively lacking." (PMID 40342824, 2025).
central nervous system disorder (1 paper, 2023). A disease involving the central nervous system. "Essential mutations alter enhancer activity through altered binding of key transcription factors (TFs) of embryonic neocortex, including ISL1, POU3F2, PITX1/2, and several SOX TFs, and are associated with central nervous system disorders." (PMID 36791193, 2023).
kidney diseases (1 paper, 2023). "Pitx1, IRF3, and ETS1 are also TFs involved in the pathogenesis of kidney diseases." (PMID 36967395, 2023).
myopathy (1 paper, 2017). A disease of the muscle in which the muscle fibers do not function properly. "As well in the transgenic mouse with inducible PITX1 expression and in a local myopathy induced by AAV-DUX4 injection AOs with the vivo-morpholino chemistry could reduce the target mRNA levels while PMOs were not efficient." (PMID 28273791, 2017).
PITX1 also shares sentences with these, for which no sentence is quoted: Barrett adenocarcinoma (2 papers); oral squamous cell carcinoma (2); polydactyly (2); acute leukemia (1); albinism (1); arthrogryposis (1); Barrett esophagus (1); Beals syndrome (1); bladder tumors (1); bone fracture (1); COVID-19 (1); cryptorchidism (1); diabetes (1); ductal breast carcinoma (1); esophageal adenocarcinoma (1); facioscapulohumeral muscular dystrophy (1); Human papillomavirus infection (1); idiopathic osteoporosis (1); invasive ductal breast carcinoma (1); invasive lobular breast carcinoma (1); ischemic stroke (1); kidney cancer (1); lymph node metastasis (1); lymphoma (1); medullary breast carcinoma (1); metastasis (1); Mirror image polydactyly (1); muscle atrophy (1); muscular dystrophy (1); nutritional deficiency (1).
A further 14 diseases each share a sentence with PITX1 in 1 paper.